PER2 (period circadian regulator 2)
Diseases named in the same sentence as PER2 in open-access papers (continued):
Sharing a sentence is not in itself a finding about the gene and the disease.
tumor (continued). "Low levels of KMT2D induce carcinogenesis via epigenetic modifications, repressing the expression of Period Circadian Regulator 2 (PER2) gene, which regulates tumor-promoting glycolytic genes." (PMID 33602320, 2021). "Mechanistically, KMT2D was found to upregulate the circadian rhythm repressor PER2 which plays an important role in tumor suppression." (PMID 35071240, 2021). "Suppression of PER2 at both gene expression and protein levels facilitates tumor growth, invasion and cancer malignancy." (PMID 34257372, 2021). "Notably, PER2 has been shown to have tumor suppressive role through regulating the expression of multiple glycolytic genes, indicating that CK1δ/ε may be implicated in tumor-promoting glycolysis via the regulation of PER2 stability." (PMID 33754069, 2021). "PER2 was a well-known clock gene, regulating circadian rhythm in human beings, whose downregulation was related with tumor initiation and progression in various cancers, including HNSCCs 39-42." (PMID 34335939, 2021). "We grew FACS sorted YFP+ tumor epithelial cells in vitro and transduced the PER2:Luc construct in these cells using lentiviral particles." (PMID 33810377, 2021). "The effect of biorhythm disturbance on tumor growth and metastasis has been reported in previous study, along with downregulation of per2 by jet lag condition." (PMID 33633796, 2021). "The negative correlation between oscillatory PER2 expression and capacity for mammosphere formation confirms the suppressive effect of Per2 on self-renewal and tumour initiation." (PMID 32581213, 2020). "Loss of Per2 in the TME leads to transcriptional rewiring at early stages of metastases formation, and suppresses subsequent metastatic tumor progression, highlighting Per2 as an unexpected protumorigenic mediator in the TME." (PMID 33123539, 2020). "In two different mouse models of cancer we find that expression of the core clock gene Per2 in the TME is crucial for tumor initiation and metastatic colonization, whereas another core gene, Per1, is dispensable." (PMID 33123539, 2020). "We also observed a decrease of Per2 and Cry2 expression in primary tumours of JL mice while expression levels of other core clock genes remained similar between treatments." (PMID 32581213, 2020). "Specifically, we observed reduced expression of the Per2 and Cry2 clock genes in primary tumours of JL mice." (PMID 32581213, 2020). "In cancer cells, both PER1 and PER2 were shown to act as tumor suppressors and mutations in these genes were associated with human cancer." (PMID 33123539, 2020). "Taken together with our results from the liver metastasis model, these results suggest that stromal Per2 is required for tumor formation both in the primary site as well as in the metastatic site." (PMID 33123539, 2020). "In both models, cancer cells were injected to Per2–/– and WT mice, and tumor volume was assessed at the end point." (PMID 33123539, 2020). "Expression of Per2 in drug-resistant tumor tissue was lower than that in cisplatin-sensitive tumor tissue, and that in dysrhythmic tumor tissue was lower than that in tumor tissue exposed to a normal circadian rhythm." (PMID 33083827, 2020). "In the same study, the authors genetically manipulated the circadian genes Per2 (Per2m/m) and Bmal1 (Bmal1−/−) in whole-animal bodies, exhibiting the same previous effects describes, and so, pointing out their tumor-suppressive role in lung cancer." (PMID 33042011, 2020). "In vivo tumorigenesis assays in nude mice revealed that tumor weight and volume in the Per2-OE group were significantly smaller than those in the NC group." (PMID 32284762, 2020). "The current studies reveal that the clock gene Per2 is expressed at lower levels in a variety of tumors and plays a significant tumor suppressor role." (PMID 32284762, 2020). "For example, expression of the Period2 gene (Per2), a molecular component of circadian clocks, has been found to have tumor-suppressive effects." (PMID 33371502, 2020).
tumor (continued). "As seen from the growth curve of subcutaneous tumors, tumor growth was slower in the Per2-OE group compared with that in the controls (P < 0.05)." (PMID 32284762, 2020). "Previous studies showed that Per2 plays an important role in tumour suppression as its knockdown increases the stemness of mammary epithelial and cancer cells." (PMID 32581213, 2020). "Compared with the PER2 overexpression group, we observed an increased phenotype in the tumor weight of subcutaneous xenografts formed by oxaliplatin‐treated OSCC cells overexpressing both PER2 and PCNA." (PMID 31728273, 2019). "miR-34a expression in tumour tissue correlated with the expression of its predicted target gene PER2, which was analysed previously." (PMID 31658284, 2019). "Bmal1 and Per2 have been demonstrated to have tumor suppressor activities and alteration of their promoter methylation has been linked with poor clinical outcome and tumor progression in hematological malignancies and gliomas." (PMID 31040792, 2019). "PER2 is believed to exert a tumour suppressive role; therefore, in this respect, miR-34a does not seem to play a beneficial role for patients." (PMID 31658284, 2019). "The expression of PER2 was significantly down-regulated in tumour tissue compared to adjacent tissue." (PMID 31658284, 2019). "Since the circadian feature of PER2 expression in peripheral blood of tumor‐bearing mice is consistent with that in OSCC tissue, it is feasible to utilize PER2 in peripheral blood as a biomarker to guide chronomodulated drug delivery of DNA‐damaging agents." (PMID 31728273, 2019). "In this context, Per family member Per2 was shown to regulate fibronectin expression which is crucial for tumor cell motility." (PMID 30971765, 2019). "PER1 and PER2 genes are considered to be tumor suppressor genes and their decreased expression has been reported in head and neck cancer." (PMID 31040792, 2019). "First, we observed a significant reduction in the tumor weight of xenografts upon overexpression of PER2 and an apparent tumor weight increase in PER2 knockdown xenografts." (PMID 31728273, 2019). "We set to assay the effect of PER2 expression on tumor weight of subcutaneous xenografts formed by oxaliplatin‐treated OSCC cells." (PMID 31728273, 2019). "Similar functions have been observed in human studies, where PER1 and PER2 in normal cells promote apoptosis and act as tumor suppressor genes." (PMID 29958276, 2018). "Per1- and Per2-mediated tumor-repressing effect is more specific to early light and early dark phase." (PMID 29607311, 2018). "Accordingly, the aberrant expression of clock core genes such as CRY1, PER1, and PER2 has been shown to impact tumor progression in colorectal, prostate, and breast cancers, respectively." (PMID 29946530, 2018). "Overexpression of Per1 and Per2 inhibits the growth of cancers cells and increases apoptosis in tumor cells." (PMID 28620312, 2017). "The tumor suppressor PML has been shown to directly interact with PER2 and regulate its nuclear localization." (PMID 28674522, 2017). "The loss of functional PER2 was predicted to lead to an enhanced proliferation, which is consistent with PER2 being reported as a tumor suppressor gene." (PMID 28351863, 2017). "Deregulation expression of c-Myc is suggested as a key factor leading to tumor development in Per2 mutant mice." (PMID 28620312, 2017). "Aberrant Per2 expression results in potent downstream effects on both cell cycle and apoptotic targets, which is suggestive of a tumor suppressive role for Per2." (PMID 27036047, 2016).
tumor (continued). "Of note, PER2 has been previously demonstrated to play a key role as tumor suppressor, by regulating DNA damage responsive pathways." (PMID 27329729, 2016). "The circadian rhythm molecule Period2 (Per2) plays a critical role as a tumor suppressor by controlling levels of BMAL1." (PMID 27285754, 2016). "Of note, PER2 has been suggested to play a key role as tumor suppressor by regulating DNA damage response pathways." (PMID 25868389, 2015). "Concomitant with the results from population studies, in vitro studies revealed that Per1 and Per2 overexpression leads to growth inhibition and apoptosis, pointing to a tumour suppressor function of the Per family." (PMID 26288701, 2015). "The promoting effect of circadian disruption on carcinogenesis is consistent with the finding that Per2 has tumor suppressing activity." (PMID 26544624, 2015). "Per2 mutant mice display tumor-prone phenotypes and deregulation of various cyclins, proto-oncogenes, and tumor suppressors." (PMID 26029155, 2015). "Aberrant Per2 expression results in potent downstream effects on both cell cycle and apoptotic targets, suggestive of a tumour suppressive role for Per2." (PMID 26347774, 2015). "In different human lymphoma cell lines as well as in tumour cells from acute myeloid leukaemia, mRNA levels of Per2 are downregulated." (PMID 26288701, 2015). "Overexpression of Period1(Per1) and Period2(Per2) sensitizes human cancer cells to DNA damage-induced apoptosis, significantly increasing apoptosis in tumor cells." (PMID 25760074, 2015). "Down-regulated expression of PER2 has been found in many cancers in both humans and mice and often considered a tumor suppressor gene; however, we cannot explain why upregulated expression of PER2 has, to date, been found only in GC." (PMID 24708606, 2014). "PER2 gene is a key player in controlling the circadian rhythm and plays an essential role in tumor suppression." (PMID 24171174, 2013). "PER2 was the second potential miR-193b target identified in this study; PER2 is a tumour suppressor involved in regulation of the circadian rhythm, which in turn controls cellular processes such as proliferation, apoptosis, metabolism and DNA repair." (PMID 23335975, 2013). "PER2 under-expression was recently reported for 40 HNSCC primary patient tumour samples; furthermore, leukemic cells over expressing PER2 also led to a reduction in proliferation and clonogenicity, which corroborates our miR-193b phenotype." (PMID 23335975, 2013). "PER2-deficient mice are more susceptible to genetic or radiation-induced cancer, Per1 or Per2 over-expression reduces tumor growth in vivo and promotes apoptosis in vitro, while PER down-regulation promotes cancer cell growth [46-48, 52-54 (but see 56, 57)]." (PMID 21566258, 2011). "Among all the known clock genes, Per2 has been shown to play an important role in tumor progression." (PMID 22166120, 2011). "Besides its well-known activity as a clock gene, Period 2 (PER2) emerged as a tumor suppressor gene in various cancers including HCC." (PMID 40521302, 2025). "Second, additional in vivo studies are needed to determine whether PER2 reactivation alone is sufficient to reverse the metabolic effects of KDM6A phosphorylation in tumor models." (PMID 41184251, 2025). "In a study, it was observed that disruption in the cell signalling pathway or promoter methylation might affect the expression of Per2 in tumor tissues." (PMID 40495887, 2025). "Co-expression of PER2 significantly suppressed the growth of KDM6AS829D-transfected tumor." (PMID 41184251, 2025).
tumor (continued). "Studies have shown that abnormal expression of key clock genes, such as Per2, may weaken its tumor suppressor function." (PMID 41174721, 2025). "In sum, circadian clock genes PER2 plays a pivotal role during GBM tumor onset and development." (PMID 40166471, 2025). "Likewise, the tumor suppressor miR-335-5p was significantly repressed while its target genes Per2 and Tef were upregulated and this tumor suppressor regulates cell cycle and epithelial-mesenchymal transition." (PMID 38245882, 2024). "However, higher evidence for an oncogenic function was found for BMAL1 and CLOCK and higher evidence for a tumour suppressor function was found for PER2 and PER3, consistent with their role in the positive respectively negative arm of the clock network." (PMID 38378853, 2024). "Moreover, PER2 overexpression exhibits a substantial growth-inhibitory effect on mouse tumor cells, playing a vital role in tumor suppression by triggering apoptotic cell death." (PMID 39596493, 2024). "SIRT1, interacting with CLOCK-BMAL1, regulates PER2 and exosome secretion, impacting the tumor microenvironment and progression in breast and ovarian cancer, and is crucial in tumor dynamics and metastasis." (PMID 39061191, 2024). "However, when considering the tumour-suppressive effects of miR-34a, this influence seems to be rather counterproductive, as per2 possesses tumour-suppressor capacity." (PMID 37831728, 2023). "Moreover, increasing evidence has shown that PER2 acts as a tumor suppressor gene to inhibit the proliferation of tumor cells." (PMID 37069338, 2023). "Thus, PER2 promotes tumor growth of GHPA and PRLPA primarily via accelerating cell cycle progression." (PMID 37215573, 2023). "As a crucial and powerful clock gene, Per2 has been found to be involved in physio/pathological pathways in tissue development, cell differentiation, cell metabolism, cell aging, tumor development, oxidative stress, and neurobiological activities." (PMID 38084142, 2023). "We further tested the role of PER2 in development of GH3 xenograft tumor." (PMID 37215573, 2023). "Additionally, mutations of circadian genes are also present in SKCM; the most mutated genes are PER2 and PER3, which are classified as tumor suppressor genes." (PMID 37373286, 2023). "Further, jetlagged mice with PER2 upregulation have accelerated growth of GH3 xenograft tumor." (PMID 37215573, 2023). "Nevertheless, the mechanism by which PER2 affects the immune microenvironment and tumor progression in HCC remains unclear, and further research is needed to clarify the biological effects of PER2 in HCC." (PMID 38074100, 2023). "Therefore, we compared PER2 mRNA and protein expression in human HCC and paracancerous tissues and explored the relationship between PER2 expression and clinicopathological tumor characteristics." (PMID 38074100, 2023). "It was noted that the tumor of control mice showed a diurnal oscillation in the proliferation index (Ki67) with a peak level at zeitgeber time (ZT) 14 (early dark phase), paralleling the diurnal pattern of pituitary Per2 expression." (PMID 37215573, 2023). "Further, we examined the promoter methylation levels of DELMRGs and found that several genes (such as OAS2, KALRN, SLC16A7, PER2) had significantly lower methylation levels in tumor samples, while several genes (SLC6A3, CDO1, and SERPINC1) were significantly higher methylated." (PMID 37795453, 2023). "PER2 overexpression in Pca cells resulted in decreased cell growth and apoptosis, suggesting that decreased PER2 levels in PCa tissue may promote tumor progression." (PMID 36291899, 2022).
tumor (continued). "In another study, when mice with Lewis lung cancer were given doxorubicin, the expression of F4/80 and CD11c in tumor tissues, and the expression of circadian genes such Bmal1, Clock, Rev-Erb, and Per-2, as well as NF-κB and IL-6 in intraperitoneal macrophages, changed significantly." (PMID 35326729, 2022). "Interestingly, KMT2D activates expression of the tumor suppressor Per2 and thereby downregulates expression of tumor-promoting glycolytic genes in K-RasG12D–driven lung tumors." (PMID 34194626, 2021). "To determine whether PER2 oscillations had an impact on response to therapy as we found out in human eSCC cells, we treated mouse tumor epithelial cells with cisplatin for 4 h when PER2 expression is high (24 and 48 h) or when it is low (36 and 60 h)." (PMID 33810377, 2021). "Similarly, irradiated mice with genetic alterations on Per2 or Per1/2 genes accelerate salivary gland hyperplasia, teratomas, lymphoma, liver, and ovarian cancer, suggesting that Per genes act as tumor suppressor genes." (PMID 34361055, 2021). "In addition to its circadian role, PER2 exhibits tumor suppressive functions as a transcriptional suppressor in many cancers." (PMID 34257372, 2021). "Downregulation of PER2 increases Cyclin D and Cyclin E levels and increases the rate of tumor growth in breast cancer, disrupts DNA damage repair pathways and results in increased tumor growth." (PMID 35156088, 2021). "Interestingly, well differentiated tumours correlated significantly with a high expression of PER2 (p = 0.009), which gradually decreased with the differentiated state of tumours." (PMID 34440171, 2021). "Since PER2 protein level oscillates and PER2 shuttles between nucleus and cytoplasm, its protein stability and subcellular localization may also determine its tumor suppression function." (PMID 34257372, 2021). "Further characterizations revealed that stromal Per2 is also required for primary tumor formation." (PMID 33816508, 2021). "Consistently high expression of PER2 negatively regulates tumor development." (PMID 34069297, 2021). "According to our findings, the KO of PER2, which has previously been reported to act as a tumour-suppressor, led to a drastic reduction in the number of oscillating genes compared to HCT116WT cells and the strongest change in the phase distribution in all investigated periods." (PMID 34885088, 2021). "However, some previous studies also indicated that activation of PER2 can induce an increase in tumor incidence." (PMID 32185221, 2020). "Employing different orthotopic tumor models, we showed that loss of stromal Per2, but not Per1, inhibits tumorigenesis and metastasis." (PMID 33123539, 2020). "In summary, it was evident that PER2 took an important part in tumor suppression in vivo." (PMID 32185221, 2020). "Using orthotopic injection of cancer cells into clock-deficient mice, we find that stromal Per2, but not Per1, is required for tumor growth and metastatic colonization." (PMID 33123539, 2020). "Together, these results suggest that T cells do not mediate stromal Per1–/–Per2–/–-associated tumor inhibition." (PMID 33123539, 2020). "Since low expressions of Per1 and Per2 were correlated with poorer tumor cell differentiation, deeper invasion depth and worse metastasis, it was reasonable to suppose that low expression of Per1 and Per2 might result in poorer OS, as studies pointed out." (PMID 32437452, 2020). "These processes may explain why, while PER2 serves as a tumor suppressor in cancer cells, it serves as a protumorigenic factor in the TME." (PMID 33123539, 2020). "Next, we asked whether stromal Per2 is essential not only for metastatic colonization, but also for primary tumor formation." (PMID 33123539, 2020).